THBS2 (thrombospondin 2)
Description:
Adhesive glycoprotein that mediates cell-to-cell and cell-to-matrix interactions. Ligand for CD36 mediating antiangiogenic properties.
Synonyms: TSP2; EDSCLL3
Tractability: Antibody: its Gene Ontology location is reachable by antibodies, with high confidence; UniProt predicts a signal peptide or a membrane-spanning region; the Human Protein Atlas places it where antibodies can reach.
Gene: Protein-coding gene on chromosome 6 (169,215,780 to 169,254,060, reverse strand). Ensembl gene ENSG00000186340.
Subcellular location (Human Protein Atlas): Plasma membrane; Centrosome; Cytosol; Predicted to be secreted
Pathways (Reactome):
Disease: Defective B3GALTL causes PpS
Metabolism of proteins: O-glycosylation of TSR domain-containing proteins
Signal Transduction: Signaling by PDGF
Gene Ontology:
Molecular function: protein binding; extracellular matrix structural constituent; heparin binding; calcium ion binding
Biological process: negative regulation of angiogenesis; endothelial cell-cell adhesion; cell adhesion; positive regulation of synapse assembly
Cellular component: extracellular matrix; extracellular region; platelet alpha granule; thrombospondin complex; basement membrane
Genetic constraint (gnomAD): Loss-of-function variants: 45 observed, 129.49 expected, observed/expected ratio (o/e) 0.35, 90% interval 0.27 to 0.45. The upper end of that interval is the gene's LOEUF score, 0.45, which puts it in group 1 of 6, group 1 being the genes least tolerant of losing a copy. Missense variants: 1,288 observed, 1,641.7 expected, observed/expected ratio (o/e) 0.78, 90% interval 0.75 to 0.82. Synonymous variants: 639 observed, 651.48 expected, observed/expected ratio (o/e) 0.98, 90% interval 0.92 to 1.05.
Homologues: Orthologues: macaque THBS2 (99% identical), dog THBS2 (91% identical), pig THBS2 (89% identical), guinea pig THBS2 (89% identical), mouse Thbs2 (89% identical), rat Thbs2 (88% identical), chimpanzee THBS2 (84% identical), rabbit THBS2 (79% identical), tropical clawed frog thbs2 (75% identical), zebrafish thbs2a (71% identical), zebrafish thbs2b (69% identical), Drosophila melanogaster Tsp (33% identical). Paralogues in human: THBS1 (61% identical), THBS3 (36% identical), THBS4 (35% identical), COMP (32% identical), ISM1 (7% identical).
Diseases named in the same sentence as THBS2 in open-access papers:
THBS2 is named in the same sentence as 211 diseases in open-access papers, as found by Europe PMC text mining. Sharing a sentence is not in itself a finding about the gene and the disease. The quoted sentences say what the papers report.
gastric cancer (39 papers, 2014 to 2025). A primary or metastatic malignant neoplasm involving the stomach. "Our previous study found that bone marrow-derived mesenchymal stem cells (BMSCs) promote Helicobacter pylori (H pylori)-associated gastric cancer (GC) progression by secreting thrombospondin-2 (THBS2)." (PMID 37798762, 2023). "The significantly elevated expression of THBS2 in various cancer types, including pancreatic and gastric cancers, is associated with their diagnosis, stage, and prognosis." (PMID 35701829, 2022). "We also added CXCL12, INHBA, THBS1, and THBS2 to the correlation analysis since they are suggested as CAF markers associated with an aggressive phenotype in gastric cancer." (PMID 35739492, 2022). "In contrast, THBS2 displays an anti-angiogenic function in gastric cancer since overexpression of THBS2 is associated with good prognosis." (PMID 27513329, 2016). "Our study presents the first line of evidences that THBS2 expression is down-regulated at both mRNA and protein levels and decreased THBS2 expression is associated with the poor histological grade of gastric cancer." (PMID 25262009, 2014). "Together, our results demonstrate THBS2 is significantly associated with the clinical prognosis of gastric cancer patients, which might become a prognostic marker for gastric cancer." (PMID 25262009, 2014). "Moreover, we observed that patients with higher levels of THBS2 were significantly correlated with more favourable prognosis while decreased THBS2 expression were associated with poorer histological grades of gastric cancer." (PMID 25262009, 2014). "Thus, our study expounded that serum THBS2 could serve as a vital early diagnostic marker for patients with gastric cancer." (PMID 34659407, 2021). "Recent studies also suggested the combined effect of VCAN and THBS2 to accelerate the growth of gastric cancer." (PMID 41451347, 2025). "By analyzing gene expression patterns through single-cell RNA sequencing, we found that several key genes, including SPARC, THBS2, COL1A1, and INHBA, are linked to poor prognosis in gastric cancer." (PMID 40075643, 2025). "On the contrary, THBS2 plays a role in promoting cell proliferation both in gastric cancer and uveal melanoma cells through the modulation of the PI3k-Akt signaling pathway." (PMID 38339060, 2024). "We identified several genes, including FN1, COL1A2, THBS2, COL3A1, COL5A1, and BGN, which appear to be associated with poorer outcomes for stomach cancer patients." (PMID 38610959, 2024). "The expression of COL1A2, COL6A3, and THBS2 genes leads to the development, migration, and invasion of gastric cancer cells, and reduces apoptosis through the PI3K-Akt pathway." (PMID 37361568, 2023). "THBS2 protein was positively expressed in 87.18% (68/78) gastric cancer tissues and 59.09% (13/22) of gastritis tissues." (PMID 36842141, 2023). "Association between the protein expression of THBS2 and VCAN and clinicopathologic parameters in 78 patients with gastric cancer." (PMID 36842141, 2023). "In our study, THBS2 protein has higher expression in gastric cancer than in gastritis and was adverse prognostic factor for gastric cancer patients." (PMID 36842141, 2023). "Mounting evidence indicate that silencing of THBS2 had the ability to inhibit the proliferation, migration, and invasion capabilities of gastric cancer cells, in accord with our present findings for NSCLC cells in vitro." (PMID 36609437, 2023). "Studies have reported high expression of THBS2 in gastric cancer tissues and worse prognosis in patients with higher THBS2 expression." (PMID 37798762, 2023). "In our study, we introduced a potential signature model for gastric cancer survival prediction, including THBS2, BAIAP2-AS1, LINC01215, and TSIX." (PMID 38162289, 2023). "These researchers observed that THBS2 was overexpressed in gastric tumor tissues and proposed THBS2 as a prognostic indicator of gastric cancer, in which high THBS2 expression was correlated with poor prognosis." (PMID 37798762, 2023).
gastric cancer (continued). "Most importantly, we partially validated the role and mechanism of THBS2 in pancreatic and gastric cancers in vitro using PANC1 and BGC-823 cell lines." (PMID 35701829, 2022). "This study aims to investigate thrombospondin 2 (TSP2) expression levels in gastric cancer (GC) and determine the relationship between TSP2 and clinical characteristics and prognosis." (PMID 35255858, 2022). "Numerous studies have strongly suggested that THBS2 is an oncogene and involved in the malignant phenotype of different tumors, such as gastric cancer, lung cancer, and osteosarcoma." (PMID 36405394, 2022). "An in vitro study showed that THBS2 silencing inhibited the proliferation, migration and invasion of gastric cancer cells." (PMID 35186032, 2022). "Consistently, we also found that THBS2 is upregulated in colon cancer, gastric cancer, and pancreatic cancer using the TCGA database." (PMID 34804159, 2021). "THBS2 was upregulated in gastric cancer tissue compared with normal tissue via analyzing data obtained from The Cancer Genome Atlas (TCGA) database." (PMID 34659407, 2021). "The load of THBS2 in tumor tissues and normal tissues of patients diagnosed with gastric cancers was analyzed by deferential analysis as well as paired differential analysis on the basis of data from The Cancer Genome Atlas (TCGA) database." (PMID 34659407, 2021). "Downregulating THBS2 exerts utterly opposite functions on the clinical outcome of sufferers with gastric cancer." (PMID 34659407, 2021). "Bone marrow mesenchymal stem cells transplanted in mice with chronic H pylori infection gradually migrate from the subserosa to the mucosa and secret THBS2 protein to promote the occurrence and development of gastric cancer." (PMID 34435402, 2021). "Diametrically opposite effects of down-regulation of THBS2 on the prognosis of patients have also been reported in gastric cancer and colorectal cancer." (PMID 31296790, 2019). "As revealed by the Kaplan–Meier plotter analysis, the survival of gastric cancer patients with high THBS2 expression was better than that of patients with low expression." (PMID 27513329, 2016). "The expression of THBS2 was significantly increased in colon, esophagus, lung, and stomach cancers as analyzed using the GENT database." (PMID 27016420, 2016). "On the other hand, decreased THBS2 expression predicted a poor survival rate in patients with gastric cancer." (PMID 27513329, 2016). "Collectively, our findings emphasized on the important roles of THBS2 in prognostic significances as well as tumour proliferation and angiogenesis in gastric cancer." (PMID 25262009, 2014). "Taken together, our results demonstrates that THBS2 is down-regulated in gastric cancer in both mRNA and protein levels." (PMID 25262009, 2014). "The mRNA and protein expression levels of THBS2 were assessed in 14 paired of gastric cancer specimens and corresponding normal mucosas using quantitative real-time PCR and western blot analysis." (PMID 25262009, 2014). "In conclusion, our discoveries demonstrate that THBS2 is inverse correlated with MVD in gastric cancer." (PMID 25262009, 2014). "Taken together, we believed that THBS2 was more likely to be down regulated in gastric cancer cell versus normal mucosa." (PMID 25262009, 2014). "In order to determine the expression levels of THBS2 in gastric cancer, we first evaluated the mRNA expression levels of THBS2 in gastric cancer by quantitative real-time in the second cohort." (PMID 25262009, 2014). "Consistently, tissue microarray (TMA) results showed THBS2 levels were also inhibited in gastric cancer tissues compared with the normal controls." (PMID 25262009, 2014). "Our study suggests THBS2 is aberrantly expressed in gastric cancer and plays a critical role in cancer progression, which can be a potential prognosis predictor of gastric cancer." (PMID 25262009, 2014).
gastric cancer (continued). "We found THBS2 proteins were mainly expressed in the cytoplasms of gastric cells, and in accordance with the results of western blot, the levels of THBS2 were significantly inhibited in gastric cancer tissues compared with the normal controls (P < 0.05)." (PMID 25262009, 2014). "In summary, our data support that THBS2 impedes the growth of gastric cancer cells in vitro possibly via the regulation of apoptosis." (PMID 25262009, 2014). "Collectively, our results imply that THBS2 suppresses the angiogenesis of gastric cancer cells in vitro." (PMID 25262009, 2014). "To examine the relationship between THBS2 expression and the clinical prognosis of gastric cancer patients, we conducted survival analyses by univariate and multivariate Cox’s proportional hazards regression model." (PMID 25262009, 2014). "85.71% (12 of 14) gastric cancer tissues expressed remarkably lower THBS2 in both mRNA and protein levels than the corresponding normal controls." (PMID 25262009, 2014). "Crucially, overexpression of THBS2 has a significant correlation with favourable prognosis of gastric cancer patients." (PMID 25262009, 2014). "Collectively, our findings suggest that THBS2 is inverse correlated with histological grade of gastric cancer." (PMID 25262009, 2014). "THBS2 levels were markedly lower in 85.7% (12 of 14) of the gastric cancer tissues than its normal controls, while the remaining two pairs of the samples exhibited the opposite." (PMID 25262009, 2014). "THBS2 is highly expressed in the stroma of gastric cancer patients." (PMID 37798762, 2023). "Moreover, thrombospondin-2 was confirmed as being expressed at high levels in more advanced gastric cancer by both the GEO and TCGA databases." (PMID 36969001, 2023). "THBS2 is also a potential prognostic biomarker of colorectal, pancreatic, and gastric cancers." (PMID 35701829, 2022). "First, we found that COL5A2, COL12A1, BGN and THBS2 were highly expressed in gastric cancer." (PMID 36447214, 2022). "For instance, lower-expressed THBS2 is related to the poor prognosis of patients with gastric cancer, cervical cancer, and ovarian cancer, while overexpressed THBS2 is related to the poor prognosis of patients with prostate cancer, lung cancer, and oral cancer." (PMID 36118676, 2022). "THBS2 levels were correlated with favorable prognosis of gastric cancer." (PMID 34471634, 2021). "In gastric cancer, THBS2 is positively correlated with THBS1, THBS3, and THBS4." (PMID 34804159, 2021). "To further verify whether THBS2 regulates tumor metastasis, we performed more experiments using colorectal and gastric cancer cells." (PMID 34804159, 2021). "The THBS2 protein has been thought to inhibit EMT in gastric cancer." (PMID 33206629, 2020). "Interestingly, in many other carcinomas, THBS2 was found downregulated and was correlated with poorer prognosis in tumors such as gastric cancer, prostate cancer and breast cancer." (PMID 28424419, 2017). "However, THBS2 exhibited an antiangiogenic function in gastric cancer as overexpression of THBS2 is correlated with improved clinical outcomes." (PMID 27513329, 2016). "In addition, colony formation assay, endothelial cell tube formation assay, cell migration assay and apoptosis analysis were carried out in MKN-45 and SGC-7901 cell lines to explore the in vitro effect of THBS2 in gastric cancer cells." (PMID 25262009, 2014). "Nevertheless, the functions and clinical significance of THBS2 still remains unclear in gastric cancer." (PMID 25262009, 2014). "However, the detailed function of THBS2 in gastric cancer and its implications for clinical diagnose still remain dismal." (PMID 25262009, 2014). "We confirm that, with the gradual depth studies of THBS2, it may be a promising useful and simple biomarker for predicting clinical outcome for gastric cancer patients." (PMID 25262009, 2014). "However, one previous research reported THBS2 mRNA expression levels in gastric cancer were higher than normal control." (PMID 25262009, 2014).
gastric cancer (continued). "Moreover, GSEA was employed to uncover that THBS2 positively related with the MAPK and Wnt-β/catenin signaling pathway, implying the potential regulatory mechanism of serum THBS2 on gastric cancer first, eventhough it was also necessary to conduct more experiments to explore the detailed mechanisms." (PMID 34659407, 2021). "Moreover, the overexpression of THBS2 had been demonstrated to be positively correlated with node metastasis and over survival in many types of cancer, including colorectal adenocarcinoma, myxoid liposarcoma, prostate cancer, and gastric cancer." (PMID 31608101, 2019). "Thirdly, our results showed that THBS2 could suppress angiogenesis of gastric cancer." (PMID 25262009, 2014). "Because THBS2 was significantly down-regulated in gastric cancer, we inferred that THBS2 might inhibit growth, promote apoptosis and enhance the migration ability of gastric cancer cells." (PMID 25262009, 2014). "Thus, we attempted to unveil the clinical significance of THBS2 and its effect in gastric cancer." (PMID 25262009, 2014). "Protein-level validation using immunohistochemistry (IHC) data from the HPA database revealed that THBS2, CTNNB1, COL4A1, and E2F3 exhibited markedly higher staining intensity in gastric cancer tissues compared to normal gastric mucosa." (PMID 41291892, 2025). "Our analysis identified hsa-miR-9-3p and hsa-miR-9-5p as shared regulators of COL4A1, CTNNB1, THBS2, and E2F3, a pattern that aligns partially with earlier studies reporting dysregulation of the miR-9 family in gastric cancer." (PMID 41291892, 2025). "The protein expression of THBS2 and VCAN in gastric cancer was significantly higher than that in gastritis." (PMID 36842141, 2023). "Our study found that compared with gastritis patients, THBS2 and VCAN were up-regulated in gastric cancer patients, and these individuals had a shorter survival time." (PMID 36842141, 2023). "IHC was used to explore the protein expression of THBS2 and VCAN in the gastric cancer and gastritis." (PMID 36842141, 2023). "For example, two protumorigenic proteins, inhibin subunit beta A (INHBA) and thrombospondin 2 (TSP2), are secreted from CAFs to the TME via extracellular vehicles, found to be an HSF1-dependent mechanism that promotes gastric cancer." (PMID 37153737, 2023). "Our in vitro results confirmed that THBS2 knockdown inhibited CD47 and MMP-2 expression and the progression of pancreatic and gastric cancers." (PMID 35701829, 2022). "In our present study, we first analyzed data from the TCGA database and found that THBS2 was upregulated dramatically in gastric cancer tumor, which indicated that THBS2 might exert a crucial role in GC." (PMID 34659407, 2021). "Then, we selected and validated three genes including THBS2, OSMR and CHI3L1 in Iranian gastric cancer patients." (PMID 33585016, 2020). "Immunohistochemistry of THBS2 and CD34 on population-based tissue microarrays consisting of 129 gastric cancer cases were used to evaluate the prognostic significance of THBS2 and microvessel density (MVD) of each sample." (PMID 25262009, 2014). "Whether THBS2 and VCAN have mutual cooperation in promoting the growth of gastric cancer needs further study too." (PMID 36842141, 2023). "Overall survival analysis of hub genes, analysis by comparative toxicogenomics database for hub genes in gastric cancer, THBS2 and VCAN protein expression by immunohistochemistry for gastric cancer and gastritis as well as design of the biological process (BP) neural network was implemented." (PMID 36842141, 2023). "Gastric cancer patients with high expression levels of FN1 (HR = 1.54, P < 0.05), MAC25 (HR = 1.48, P < 0.05), THBS2 (HR = 1.55, P < 0.05), VCAN (HR = 1.32, P = 0.0031), SPARC (HR = 1.42, P < 0.05), MSLN (HR = 1.28, P = 0.0066), and FGA (HR = 1.37, P < 0.05) had shorter survival time." (PMID 36842141, 2023). "In summary, THBS2 and VCAN may be potential targets for improving gastric cancer patients' diagnosis and clinical efficacy." (PMID 36842141, 2023).